SIRT2 (sirtuin 2)
Diseases named in the same sentence as SIRT2 in open-access papers (continued):
Sharing a sentence is not in itself a finding about the gene and the disease.
breast cancer (continued). "In basal-like breast cancer, SIRT2 can be overexpressed and stabilize EMT-TF Slug to promote tumor invasion and stem-like phenotypes." (PMID 40165290, 2025). "For instance, in breast cancer cells, SIRT2 was shown to inhibit peroxiredoxin‐1 via deacetylation, which decreased its antioxidant peroxidase activity." (PMID 39215785, 2025). "On-target Sirt2 inhibition by ICL-SIRT078 was observed in the MCF7 breast cancer cell line via increased acetylation of the Sirt2 substrate α-tubulin." (PMID 38474697, 2024). "On the other hand, NOTCH signaling promotes breast cancer stem cells by activating ALDH1A1 through the induction of SIRT2, which results in ALDH1A1 deacetylation and enzyme activation." (PMID 39479446, 2024). "In human breast cancer, mixed roles for Sirt2 have also been observed, with grade 1 tumors displaying decreased Sirt2 expression and higher-grade tumors showing elevated expression." (PMID 37628798, 2023). "Sirtinol B has been known as a human sirtuin-2 (SIRT2) inhibitor, which is reported to induce senescence-like growth arrest in human breast cancer MCF-7 cells and lung cancer H1299 cells." (PMID 37800155, 2023). "In summary, SIRT2 is highly involved in the initiation and progression of breast cancer, playing either a tumor-promoting or tumor-suppressing role." (PMID 36291902, 2022). "Studies have shown that SIRT2 expression is downregulated in breast cancer tissues compared to normal breast tissues." (PMID 36291902, 2022). "In this regard, studies have investigated the tumor-suppressing or tumor-promoting mechanisms of SIRT2 in breast cancer." (PMID 36291902, 2022). "Overall, their findings indicate a tumor-suppressing role of SIRT2 in breast cancer through the promotion of normal mitosis." (PMID 36291902, 2022). "BZD9L1 is another SIRT-1 and SIRT-2 inhibitor able to induce apoptosis in colorectal, leukemia, and breast cancer cell lines." (PMID 36080416, 2022). "In breast cancer, SIRT2 can be activated by NOTCH signalling, leading to the deacetylation and activation of high aldehyde dehydrogenase (ALDH1A1), thereby promoting breast cancer progression." (PMID 36101744, 2022). "SIRT2 has been reported to be highly expressed and frequently amplified in basal-like breast cancer (BLBC)." (PMID 35406775, 2022). "Compound 3g, designed by Laaroussi and colleagues, proved to be an SIRT-1 and SIRT-2 inhibitor with cytotoxic effects on leukemia, colorectal, lung and breast cancer cell lines." (PMID 36080416, 2022). "Utilizing E0771 mouse breast cancer cells, we repeated the experiments in Sirt2-KI and WT mice and observed them for 27 days." (PMID 34155309, 2021). "This work gives new information on the expression of SIRT1 and SIRT2 levels in individuals in the case of radiotherapy in breast cancer patients." (PMID 33705642, 2021). "On the other hand, SIRT2 can reduce the activity of peroxiredoxin-1 (Prdx-1) through deacetylation which leads to breast cancer cells accumulating reactive oxygen species (ROS) and becoming less viable." (PMID 34368168, 2021). "For instance, SIRT2 can promote breast cancer development by deacetylating Slug and aldehyde dehydrogenase 1A1 (ALDH1A1)." (PMID 34368168, 2021). "SIRT2 knockdown in MCF7, MDA-MB-468, and MDA-MB-231 breast cancer cells reduced the cell proliferation, confirming that SIRT2 inhibition or perturbation induces cytotoxicity." (PMID 34650436, 2021). "Studies have shown that SIRT2 is remarkably downregulated in human breast cancers and hepatocellular carcinoma (HCC) samples." (PMID 31932479, 2020). "In the present study, we sought to examine the expression of SIRT2 in T lymphocytes of breast cancer patients and normal individuals." (PMID 33061819, 2020). "In this study, we found significantly lower expression of SIRT2 in peripheral T lymphocytes from breast cancer patients when compared to normal individuals." (PMID 33061819, 2020).
breast cancer (continued). "Here, we discovered previously unrecognized function of SIRT2 in regulating T-cell-mediated immune response: T lymphocytes in breast cancer patients showed decreased SIRT2 expression compared to healthy controls." (PMID 33061819, 2020). "The lower SIRT2 expression in T lymphocytes suggested insufficient antitumor immunity in breast cancer patients." (PMID 33061819, 2020). "In this review, we will discuss the divergent expression and function of SIRT2 in five malignancies: breast cancer, non-small cell lung cancer, HCC, colorectal cancer, and glioma." (PMID 33014852, 2020). "To explore the role of SIRT2 in antitumor immunity, we examined SIRT2 mRNA expression in the peripheral blood CD3+ T cells from breast cancer patients and normal individuals." (PMID 33061819, 2020). "The oncogenic role of SIRT2 has been identified in basal-like breast cancer cells and hepatocellular carcinoma 27, 37, and the interruption of SIRT2 catalytic activity was reported to potentially target a subset of c-Myc-driven cancers." (PMID 32104503, 2020). "In this study, we have found that SIRT2 participate in T-cell-mediated immune response in breast cancer." (PMID 33061819, 2020). "In breast cancer, lower SIRT2 expression was detected in cancer tissues as compared with adjacent normal tissues." (PMID 33207824, 2020). "NAM doses between 5 and 20 mM are known to induce mitophagy with a mechanism likely related to the NAD+ increase; apoptosis and mitophagy were shown to be SIRT2 dependent in the highly aggressive MDA-MB-231 breast cancer cells." (PMID 33028392, 2020). "Although SIRT2 expression was lower in breast cancer than in normal tissue, residual SIRT2 expression was generally observed." (PMID 33014852, 2020). "Using a tissue array with 36 paired samples of breast cancer and adjacent normal breast tissue, they demonstrated significantly higher levels of SIRT2 in normal breast tissues compared with cancer tissues." (PMID 33014852, 2020). "Contrary to SIRT1 and SIRT2, SIRT3 is reported to have an opposing effect on angiogenesis, as loss of SIRT3 in human breast cancers, resulted in the upregulation of HIF-1α target genes like VEGF and genes involved in glycolysis." (PMID 32010617, 2019). "Conversely, in poorly differentiated breast cancers, such as grade 3 breast tumors, SIRT2 expression levels are high and are responsible for further dysregulation of cell cycle progression and DNA repair processes." (PMID 30761005, 2019). "For example, increased expression of SIRT2 is observed in breast cancer, and inhibition of SIRT2 significantly inhibits breast cancer growth." (PMID 30584257, 2018). "Selective SIRT2 inhibitors induce cell death in non-small cell lung cancer and breast cancer cell lines." (PMID 30081901, 2018). "In MDA-MB-231 and MCF-7 breast cancer cell cultures, 36 showed antiproliferative activity with selective acetylation the SIRT2 substrate α-tubulin." (PMID 28989670, 2017). "We have recently uncovered the novel finding that SIRT2’s capacity to function as tumour promoter, or suppressor in breast cancer, is dependent on the grade of breast tumour." (PMID 26121130, 2015). "However, SIRT2 expression was shown to sensitize breast cancer cells to oxidant stress-inducing agents by modulating peroxidase activity." (PMID 40165290, 2025). "Moreover, the SIRT2‐24a co‐crystal structure enabled the structure‐based campaign that led to compound 25a which shows great potency and selectivity against SIRT2 and exhibits anticancer activity in breast cancer cells." (PMID 39215785, 2025). "Additionally, SIRT2 contributes to tumorigenesis and prognosis of breast cancer, and depending on the tumor grade, it can either promote or suppress growth." (PMID 41304967, 2025). "SIRT2 expression in peripheral T lymphocytes of breast cancer patients is significantly reduced." (PMID 41425553, 2025).
breast cancer (continued). "Despite its therapeutic efficacy in breast cancer models, the poor aqueous solubility and laborious synthesis of the TM pseudopeptide Sirt2 inhibitor inspired conversion to thiocarbamoyl pseudopeptide analogs with improved solubility and decreased hydrophobicity." (PMID 38474697, 2024). "SIRT2 promotes breast cancer CSCs via Notch–autophagy connections and ALDHA1A deacetylation." (PMID 38397988, 2024). "Compound 26, the most potent of these next-generation TM pseudopeptides, exhibited on-target Sirt2 inhibition in MCF7 breast cancer cells, as demonstrated by increased acetylation of perinuclear α-tubulin; Compound 26 also decreased MCF7 cell migration, a proxy for metastatic potential." (PMID 38474697, 2024). "Novel CRBN recruiting PROTACs that may effectively degrade SIRT2 in a variety of breast cancer cells have been published recently." (PMID 37667522, 2023). "This could have translational relevance, as one recent study showed SIRT2 expression to be significantly lower in peripheral T-lymphocytes of breast cancer patients, which suggested insufficient antitumor immunity due to compromised detection of tumor cells." (PMID 37628798, 2023). "Furthermore, SIRT2 was shown to be predominantly involved in the tumorigenesis and prognosis of breast cancer and that, depending on the tumor grade, SIRT2 acts as either a tumor suppressor or tumor promoter in breast tumors." (PMID 36291902, 2022). "In contrast, CD8+ T cells and NK cells can effectively eliminate tumor cells in breast cancer, suggesting that SIRT-2 may also be a tumor suppressor factor." (PMID 35906622, 2022). "Moreover, the SIRT2 protein level was significantly increased in aldehyde dehydrogenase 1-positive (ALDH1+) breast cancer stem cells (CSCs) isolated from primary human breast tumors." (PMID 35406775, 2022). "In breast cancer, SIRT2 not only promotes tumours but also suppresses tumours." (PMID 36101744, 2022). "For example, SIRT2 can inhibit the antioxidant activity of peroxiredoxin-1 (Prdx-1), rendering breast cancer cells sensitive to ROS-induced DNA damage and cytotoxicity, leading to apoptosis in breast cancer cells." (PMID 36101744, 2022). "Furthermore, SIRT2 has an important role in breast cancer, hepatocellular carcinoma and other tumors." (PMID 35177983, 2021). "With our present results, we could clearly say that down-regulation of soluble SIRT2 level in human breast cancer with radiotherapy may be affected to stop or at least slowdown tumorigenesis." (PMID 33705642, 2021). "Additionally, by emphasizing the importance of SIRT2 in breast cancer, it opens ways to provide grounds for the development of the next generation of SIRT2-specific radiotracers." (PMID 33705642, 2021). "In breast cancer cells, SIRT2 could stop the peroxiredoxin-1 activity, increase the responsiveness of breast cancer cells to reactive oxygen species stimulated DNA damage and so encourage the apoptosis of cancer cells." (PMID 33705642, 2021). "Therefore, it shows biological roles that SIRT1 and SIRT2 play in the human organism in connection with radioactivity therapy during breast cancer treatment." (PMID 33705642, 2021). "Also, SIRT2 deacetylates K116 of Slug, which subsequently stimulates the growth of basal-like breast cancer." (PMID 34650436, 2021). "In other words, this present article discusses whether radioactivity has an activating or inhibiting effect on individual SIRT1 and SIRT2 proteins in breast cancer." (PMID 33705642, 2021). "Our findings of SIRT2 expression due to radioactivity in breast cancer was compared with SIRT1 expression showed that SIRT2 may clearly play an important role in breast cancer." (PMID 33705642, 2021). "As it was also observed with the present study and the debatable duties of SIRT1 and SIRT2 in cancer; it could be thought that more examination on the appearance proportion of soluble SIRT1 and SIRT2 proteins in human (breast) cancer needs to be done." (PMID 33705642, 2021).
breast cancer (continued). "The role of SIRT2 in tumorigenesis has been extensively studied in breast cancer." (PMID 33014852, 2020). "While it is downregulated in many cancers such as breast cancer, prostate cancer, human gliomas, neck squamous cell carcinoma, colorectal cancer and leukemia, we report here, according to other studies, that SIRT2 is upregulated in melanoma." (PMID 33028392, 2020). "SIRT2 levels positively correlated with CD8+ TEM cells in breast cancer patients." (PMID 33061819, 2020). "Taken together, SIRT2 may have a significant tumor suppressive role during early carcinogenesis of breast cancer, but conversely in advanced cancer, its overexpression portends more aggressive phenotype, and SIRT2 inhibition has anticancer activities." (PMID 33014852, 2020). "Moreover, SIRT2 levels positively correlated with CD8+ effector memory T (TEM) cells in breast cancer patients." (PMID 33061819, 2020). "Similarly, studies focused on CSCs (cancer stem cells) and BLBC (basal-like breast cancer) suggest SIRT2 as an oncogene." (PMID 33014852, 2020). "In addition, overexpressed HDAC2 and SIRT2 as well as nearly depleted SIRT3 were observed in the aggressive basal-like breast cancer cells." (PMID 33194676, 2020). "Taken together, a lower expression of SIRT2 in breast cancer compared with that in normal breast indicates that SIRT2 might act as a tumor suppressor at the initiation of tumorigenesis." (PMID 33014852, 2020). "Several studies focused on the clinical relevance of SIRT2 expression in breast carcinoma." (PMID 33014852, 2020). "In breast cancer progression, SIRT2 function depends on the grade and classification of the tumor." (PMID 30761005, 2019). "Furthermore, it has been reported that SIRT2 directly deacetylates Slug to prevent Slug protein degradation and then promotes basal-like breast cancer development." (PMID 30584257, 2018). "Moreover, 36 shows highly potent and selective SIRT2 inhibition with antiproliferative activity in breast cancer cells and potent neurite outgrowth activity in neuro-2a (N2a) cells." (PMID 28989670, 2017). "Interestingly, SIRT2 expression was significantly lower in breast cancer than in normal breast tissue, suggesting that SIRT2 may act as a tumor suppressor during the initiation of tumorigenesis." (PMID 35845599, 2022). "Additionally, these results suggest that SIRT2 may provide a new strategy for follow-up of breast cancer treatment." (PMID 33705642, 2021). "This may implicate SIRT2 as a new potential therapeutic target for treating breast cancer." (PMID 33705642, 2021). "Additionally, by emphasizing the importance of SIRT2 in breast cancer, we could open ways to provide grounds for the development of the next generation of SIRT2-specific radiotracers." (PMID 33705642, 2021). "However, we could conclude from this study that the down-regulation of SIRT2 after radiotherapy could probably induce apoptosis in breast cancer." (PMID 33705642, 2021). "Therefore, the development of invasive or if possible noninvasive molecular imaging approaches for monitoring SIRT2 could be a very useful tool for breast cancer." (PMID 33705642, 2021). "We will focus on five malignancies (breast cancer, non-small cell lung cancer, hepatocellular carcinoma, colorectal cancer, and glioma) to describe the current status of SIRT2 research and discuss the clinical evaluation of SIRT2 expression and the use of SIRT2 inhibitors." (PMID 33014852, 2020). "SIRT2 enhances the metabolic fitness and effector differentiation of CD8+ T cells, promoting durable anti-tumor responses in breast cancer and glioma models." (PMID 41425553, 2025). "MHY2256 has been shown to reduce breast cancer cell viability in preclinical studies by downregulating the expression of SIRT1, SIRT2, and SIRT3." (PMID 41304967, 2025). "Pan-SIRT1–3 inhibitor NH4-6 and SIRT2-selective inhibitor NH4-13 both suppressed tumor growth, but NH4-13 had lower toxicity and comparable efficacy in a breast cancer model." (PMID 41471349, 2025).
breast cancer (continued). "Benzothiazole derivatives (7ab and 7ba) that inhibit SIRT1, SIRT2, and SIRT3 in MCF-7 breast cancer cells reduced cell proliferation with IC50 values of 11.4 μM and 9.6 μM." (PMID 41471349, 2025). "The cellular activity of Compound 64 was confirmed by increased acetylation of the Sirt2 substrate α-tubulin in a concentration- and time-dependent manner in the MCF7 breast cancer cell line." (PMID 38474697, 2024). "TM-P4-Thal specifically degraded SIRT2 in MCF7, BT549, MDA-MB-231, and MDA-MB-468 breast cancer cell lines." (PMID 37667522, 2023). "Another recent study revealed that SIRT2 positively regulates T cell differentiation, specifically the CD8+ T cells, to facilitate tumor immune response during breast cancer progression." (PMID 36291902, 2022). "It has also been confirmed that SIRT-2 can mediate the differentiation of CD8+ T cells by inhibiting glycogen synthase kinase-3β (GSK-3β) acetylation and promoting aerobic oxidation in breast cancer patients." (PMID 35906622, 2022). "We will focus on five malignancies, breast cancer, non-small cell lung cancer, hepatocellular carcinoma (HCC), colorectal cancer, and glioma, in which the pattern of SIRT2 expression and its physiologic functions are controversial." (PMID 33014852, 2020). "In several cancer cell lines, including glioma, neck squamous cell carcinoma, non-small cell lung cancer, breast cancer, prostate cancer, and HCC, SIRT2 gene is found downregulated or deleted." (PMID 30761005, 2019). "While, SIRT1, 4, 5, and 7 have been reported to be upregulated in certain cancers, the same SIRT1as well as SIRT2 and SIRT6 is shown to be downregulated in breast cancer, hepatic cell carcinoma, gliomas, gastric carcinomas and colon adenocarcinoma." (PMID 32010617, 2019). "NOTCH signaling induces SIRT2 to deacetylate ALDH1A1, leading to increased ALDH activity, CSC populations, and CSC self‐renewal in breast cancer." (PMID 28994177, 2017). "A redundancy mechanism also exists in breast cancer cells whereby silencing of both SIRT1 and SIRT2 is required to induce cell death." (PMID 22768255, 2012). "However, high SIRT2 and SIRT5 expression also correlated with drug resistance profiles across multiple breast cancer lines and chemotherapies, underscoring their roles in chemoresistance mechanisms." (PMID 41471349, 2025). "In particular, sirtuin 2 emerged as a key protein, presenting both before and after breast cancer treatments in the PPSNP compared with the non-PPSNP subgroup." (PMID 35408848, 2022). "Sirtuin 2 (SIRT2) is induced via the NOTCH signaling pathway to deacetylate aldehyde dehydrogenase A1 (ALDH1A1) at K353 leading to the increase of its enzyme activity and the promotion of breast cancer stem cells (CSCs) properties." (PMID 35216622, 2022). "Unlike in breast cancer, SIRT2 was previously shown to be highly expressed in prostate cancer cells compared with normal prostate cells." (PMID 36291902, 2022). "A recent study of genomic data also showed that the expression of SIRT2 was lower in human breast cancer and HCC samples than in normal human tissue samples." (PMID 31932479, 2020). "Moreover, SIRT2 levels and CD8+TEM showed a positive correlation in breast cancer patients (R2=0.339, P=0.009)." (PMID 33061819, 2020). "Moreover, cellular assays in MCF-7 breast cancer cells revealed that ST132 has shown an antiproliferative effect, as well as increased acetylated α-tubulin expression levels, which is typically consistent with SIRT2 inhibition." (PMID 41805109, 2026).